KRAS (KRas proto-oncogene, GTPase)
Diseases named in the same sentence as KRAS in open-access papers (continued):
Sharing a sentence is not in itself a finding about the gene and the disease.
adenoma (continued). "Clinical findings, morphologic features, immunophenotypes and KRAS alterations were investigated in 7 patients with intraductal tubular adenomas, 16 patients with gastric-type intraductal papillary mucinous neoplasms and 6 patients with intraductal tubulopapillary neoplasms." (PMID 25245835, 2014). "In contrast, the malignant transformation and accelerated adenoma-carcinoma sequence brought about by the gut-specific expression of oncogenic KRAS result in the establishment of a subpopulation of tumour-initiating cells (estimated as 1 in approx. 7×104 bulk tumour cells)." (PMID 24069241, 2013). "In this study, we confirmed that the extensive DLC-1 methylation was associated with the KRAS mutations in CRCs but not in adenomas." (PMID 23509688, 2013). "Moreover, comparing adenomas and HPs/SSAs in MAP patients, APC mutations were only detectable in adenomas, indicating two possible tumor pathways, one leading to adenomas via APC mutations, and the other leading to HPs/SSAs via KRAS activation." (PMID 22876359, 2012). "Furthermore, Abi1 is overexpressed in inflammatory mucosa, sessile serrated polyps and adenomas, tubular adenomas, invasive CRC and CRC metastasis when compared to healthy mucosa and BRAF-mutated as well as KRAS wild-type hyperplastic polyps." (PMID 22808230, 2012). "These KRAS mutation frequencies were not significantly different compared to KRAS mutation frequencies of polypoid adenomas (data not shown)." (PMID 22848674, 2012). "Recently, it was shown that β-catenin stabilization and C-terminal binding protein 1 (CtBP1) following APC inactivation contribute to adenoma initiation as the first step, and that KRAS activation and β-catenin nuclear localization act synergistically to promote adenoma progression to carcinoma." (PMID 24212796, 2011). "Constitutive activation of KRAS via mutation is a common finding in CRC, and one that has been assumed to be of importance to tumorigenesis due to its frequent and early occurrence in the adenoma-carcinoma sequence." (PMID 21910869, 2011). "KRAS mutation occurred in 26.5% and BRAF mutation in 4.8% of adenomas (all types) (P < 0.0001)." (PMID 16879389, 2006). "Enrichment and pathway analysis identified several upregulated pathways specifically in the “FAP adenoma vs. FAP normal” comparison, including the “hallmark estrogen pathway”34 and “hallmark KRAS signaling”35, both of which may play a role in tumorigenesis within the intestinal tract." (PMID 40280932, 2025). "Thus far, we have only investigated the role of wild-type KRAS in mouse models of adenoma." (PMID 38168062, 2024).
adenoma (continued). "Moreover, KRAS mutations were observed more frequently in advanced adenomas (22.0%) than in non-advanced adenomas (4.8%; P<0.0001)." (PMID 28953955, 2017). "The frequency of KRAS mutation was not different between adenoma and cancer." (PMID 27563825, 2016). "For example, the additional driver mutation could be the mutation activating the KRAS/BRAF pathway in a small colorectal adenoma, associated with the transformation from small to large adenoma, or the mutation that transforms benign adenoma into infiltrating carcinoma." (PMID 23396615, 2013). "Traditional serrated adenomas with low and high grade intraepithelial neoplasia derived from the distal colon (19% right sided versus 67% left sided) and exhibited considerably more often KRAS mutations than sessile serrated adenomas (41% BRAF mutation versus 37 % KRAS mutation)." (PMID 23045412, 2012). "We found KRAS codon 12 and 13 mutations in half of the traditional serrated adenomas (4/8, 50%) but could not detect a BRAF mutation in these lesions." (PMID 22808230, 2012). "The high frequency of KRAS mutations in serrated adenomas and serrated adenocarcinomas observed in the present study explains, in part, why KRAS mutations are less frequent in non-serrated adenomas but occur in abount 40% of CRCs." (PMID 21457162, 2011). "Because the process of adenoma formation may involve additional genes (such as KRAS), we extend the model framework to accommodate additional rate-limiting mutations for the initiation of an adenoma and generalize the mathematical derivation of their number and size distribution accordingly." (PMID 22022253, 2011). "Therefore, it is likely that the Vogelstein model was originally contaminated by observations on (traditional) serrated adenomas bearing KRAS mutations misclassified as non-serrated adenomas." (PMID 21457162, 2011). "However, among TAs < 10 mm, KRAS mutation occurred in 3/25 (12%) adenomas with no MGMT loss but in 4/8 (50%) adenomas with MGMT loss (P < 0.04)." (PMID 16879389, 2006). "This study is aimed at evaluating the frequency of KRAS-G12C and PIK3CA-Q546K in adenomas and CRC from MAP patients and to demonstrate their relevance to reclassify MUTYH VUS." (PMID 42164324, 2026). "RAS (including KRAS, NRAS, and HRAS) molecular alterations are most frequently seen in follicular carcinomas and benign adenomas." (PMID 39456540, 2024). "In conventional adenomas, CRC arises from tubular adenomas (TAs), villous adenomas (VAs), and mixed tubulovillous adenomas (TVAs), often via activation of the WNT and KRAS pathways." (PMID 39554798, 2024). "Transcriptomic analysis identified upregulation of the expression of E2F targets, KRAS and TNF-alpha signaling, and epithelial-mesenchymal transition pathways in carcinomas compared to adenomas and normal tissues." (PMID 37121965, 2023). "In the adenoma group, GNAQ, KRAS, MUC16, and TTN were identified as the driver genes, whereas in the cancer group, only GNAQ and KRAS were identified as the driver genes." (PMID 37546388, 2023).
adenoma (continued). "The model allows for the calculation of the probabilities to develop an advanced adenoma through the APC-/- and KRAS pathways, functions PAPC(t) and PKRAS(t)." (PMID 35416770, 2022). "Only the MTORC1 pathway, among all of the pathways involved in the adenoma–carcinoma sequence (WNT β-catenin, KRAS signaling up, MTORC1, and TGF-β pathways), was enriched in CRC organoids of the GSE 57965 cohort." (PMID 33668713, 2021). "The CIN pathway is the most frequent; it involves the classic adenoma-carcinoma sequence and genetic alterations in adenomatous polyposis coli—APC—(30–70%) and Kirsten Rat Sarcoma viral antigen homolog—KRAS—(30–50%)." (PMID 32676506, 2020). "Stimulation of the epidermal growth factor receptor (EGFR) leads to the activation of KRAS or phosphatidylinositol-3-kinase pathways, which is important in CRC development from early adenoma to intermediate adenoma." (PMID 29568751, 2018). "Compared with carcinoma, Fn infection in adenoma/polyps seems random, not selective to BRAF- or KRAS-mutated cases and is characterized by poor bacterial-enabling growth as indicated by a lower number of Fn copies." (PMID 37772997, 2023). "A systematic review published by INCISE identified 49 gene mutations, single nucleotide polymorphisms, or haplotypes in 23 different genes/chromosomal regions (including KRAS, APC, EGFR, and COX1/2) that predicted metachronous adenoma or advanced adenoma development." (PMID 37158435, 2023). "One was the panel consisting of methylated BMP3/NDRG4/VIM/TFPI2/mutant KRAS, β-actin, and Hb-level (and later refined and commercialized as Cologuard®), which in stool detected CRC with 87% sensitivity, adenoma with 82% sensitivity, and demonstrated a specificity of 93%." (PMID 33030559, 2021). "Somatic KRAS mutations (G12V and A146T) have also been observed above all in MMR-P adenomas, rather than MMR-D." (PMID 33923068, 2021). "In one study including two foveolar adenomas of the duodenum, both harbored GNAS mutations, while no APC, KRAS, or CTNNB1 mutations were found." (PMID 33922305, 2021).
adenoma (continued). "One major limit of liquid biopsy is the detection of only advanced BRAF- or KRAS-mutated CRC but not BRAF and KRAS wild-type CRC and adenomas." (PMID 32517177, 2020). "Additionally, we performed multiregional, targeted next-generation sequencing (NGS) of adenomas and unmasked extensive heterogeneity, affecting known drivers such as APC, KRAS and mismatch repair (MMR) genes." (PMID 30166531, 2018). "Contrary to KRAS mutant tumors, BRAFV600E-induced tumors are benign adenomas that fail to progess." (PMID 23825589, 2013). "When we examined the association of KRAS mutations to DLC-1 methylation, a statistically significant correlation was observed only in the CRCs (P = 0.010), but not in adenomas (P = 0.889)." (PMID 23509688, 2013). "KRAS-G12C was also present in 47% of 17 MAP adenomas, whereas none of them harbored PIK3CA-Q546K." (PMID 42164324, 2026). "Finally, ACSS2 plays a critical role in early KRAS G12V adenoma development, unlike in KRAS G12D adenomas." (PMID 40131933, 2025). "Also, another study concluded that an increasing burden of F. nucleatum during or after the transition of an adenoma to a carcinoma promotes the sessile serrated pathway (SSP), but not the KRAS-associated CRC carcinogenesis." (PMID 39390564, 2024). "The VAFs associated with PIGA variants in this study suggest that the variants may arise early in duodenal adenoma development in a proportion of already initiated adenomas, perhaps following APC initiating events but preceding those affecting other known tumor drivers such as KRAS." (PMID 38546397, 2024). "Sole mutations in KRAS, which do not arise in the context of prior WNT-activating mutations are exceedingly rare in adenomas, and in a murine model, a single Kras mutation resulted in senescence as opposed to hyperproliferation seen in the Apc-Kras mutational sequence." (PMID 37643866, 2023). "Interestingly, some mutations like KRAS and DNAH3 were detected in organoids but not in primary adenoma, and the multiple hit of FBXW7 was observed in O4, but only missense mutation was detected in P4." (PMID 37667332, 2023). "Specifically, the analysis of individual colonic crypts isolated from adenomas of patients with distinct hereditary polyposis syndromes, as well as from sporadic and Lynch-syndrome derived carcinomas, demonstrated that the ITH for both APC and KRAS alterations was detectable in single crypts." (PMID 33923068, 2021). "BRAF or KRAS mutations were observed in both non-dysplastic or dysplastic sessile serrated adenomas; most MLH1-deficient sessile serrated adenomas with dysplasia displayed RNF43 mutations less frequent in sessile serrated adenomas with retained MLH1 expression." (PMID 29652830, 2018). "Based on our results this could explain the reported differences for KRAS in flat adenomas observed in previous studies, since in the current study a significant difference for codon 12 was observed while for the whole KRAS gene this difference was absent." (PMID 22848674, 2012). "RNF43 mutations have been observed in BRAF-mutant sessile or traditional serrated adenomas, but not in their KRAS-mutant counterparts, suggesting that the alternate modalities of MEK–ERK pathway activation may determine the method by which the Wnt pathway is activated." (PMID 35975243, 2022).